GLI1 (GLI family zinc finger 1)
Diseases named in the same sentence as GLI1 in open-access papers (continued):
Sharing a sentence is not in itself a finding about the gene and the disease.
tumor (continued). "A C-terminal motif of Gli1, DSGVEM, has been identified to stabilize the Gli1 protein and to rapidly accelerate the tumor formation." (PMID 38307877, 2024). "Consistently, tumor masses from the SALL4-silenced group show a reduced cellularity, a significant decrease in GLI1 and the proliferation marker Ki67 expression as well as increased apoptosis as indicated by increased expression of cleaved Caspase-3 (Cl." (PMID 38062245, 2024). "Western blot showed that the protein expression levels of Shh, Smo, Gli1, andGli2 in 786-O and ACHN tumor spheres were increased after treatment withdifferent concentrations of CSE, indicating the stimulation of the SHH signaling pathway." (PMID 38985013, 2024). "In this review, we delve into the diagnosis and therapeutic implications of neoplasms with genetic alterations involving the chromosomal region 12q13-15, mainly MDM2, CDK4, and GLI1." (PMID 38275873, 2024). "Regarding tumor tissues, TGCT, MESO, and SKCM exhibited the highest levels of GLI1, GLI2, and GLI3, respectively." (PMID 38498906, 2024). "Elevated levels of Gli1 and Sufu in MBs that spontaneously developed in Ptch1–/+ mice prompted us to determine if this was also the case in humans by examining GLI1 and SUFU expression in a tumor tissue array containing 49 unstratified MB specimens." (PMID 38358805, 2024). "These neoplasms typically express CD56, S100, and p16 and are predominantly located in the head and neck region, displaying alterations in the GLI1 gene." (PMID 38275873, 2024). "Genistein, an isoflavone derived from Genista tinctoria, has drawn attention in recent years for its ability to suppress GLI1, particularly within the CSC niche, across various tumour types." (PMID 38920995, 2024). "Our staining results of 190 samples show that expression of GLI1, GLI3, KRT16, and S100A7 was mostly detected in the epidermal layer overlying or bordering the tumor mass." (PMID 38892279, 2024). "In situ hybridization further confirmed significant expression of SHH pathway proteins, including SMO, GLI1, GLI3, and SUFU, indicating an active role of SHH signalling in promoting tumour cell proliferation and maintenance." (PMID 39568072, 2024). "This confers increased activity to GLI1, thereby enhancing SHH signaling and sustaining cell proliferation and tumor onset." (PMID 38062245, 2024). "Indeed, the two SMURFs can interact with GLI1, exploiting the proline rich regions present on GLI1 protein, and trigger its polyubiquitination and proteasomal degradation, leading to a suppression of the Hedgehog pathway activity and a reduction of Hh-dependent tumor cell proliferation." (PMID 39695131, 2024). "The results demonstrated that Gli1 silencing in NCI-H1299 and NCI-H1703 cells posed passive effect on tumor angiogenesis-related processes." (PMID 38493151, 2024). "Our study underscores the critical role of GLI1 in BRCA, both as a potential tumor suppressor and an immune regulator." (PMID 39483334, 2024). "GLI1 and GLI3 were significantly positively correlated in 21 tumor tissues but negatively correlated in one tissue." (PMID 38498906, 2024). "Currently, there is limited information that allows us to understand the actual effect of GLI1 and GLI2 inhibition, although it has been demonstrated that GLI1/2 inhibitors can block tumor proliferation in mice with human tumor xenografts." (PMID 38275873, 2024). "REN maps on chromosome 17p, a region frequently deleted in SHH-MB subgroup, and acts as tumor suppressor which, by promoting degradation of HDAC1, inhibits GLI1 activity and represses SHH-MB growth." (PMID 38062245, 2024). "We show that staining of GLI1, KRT16, and S100A7 appears in the same places in the samples (same samples and different tumor slices) in all stages, while the localization of staining of GLI3 differs from the other proteins at lower stages." (PMID 38892279, 2024).
tumor (continued). "We further identify NRP1 and ITGB1 as pivotal functional receptors of Sema3C, activating downstream AKT/Gli1/c-Myc signaling pathways to bolster HCC self-renewal and tumor initiation." (PMID 38956074, 2024). "GLI1 and GLI2 have been found to have overlapping effects on tumor development, while the relationship between GLI3 and the former two is not yet fully understood." (PMID 38498906, 2024). "For instance, tumor sample CCGA-UBC-034T contained an ecDNA with seven genes, including CDK4, DDIT3, GLI1, HMGA2, PTPN11, RFC5, and TMPO." (PMID 39267784, 2024). "SHH signalling inhibitors effectively dismantle GBM cancer stem cells (CSCs) and prevent tumour recurrence by targeting SHH ligands, SMO, and GLI1 transcription factors at multiple points in the pathway." (PMID 39568072, 2024). "In tumor-induced skin, a single treatment with AFL monotherapy resulted in significant mean reductions of mRNA expression of all three hedgehog genes (Gli1, 72.4%, p = 0.003; Gli2, 55.2%, p = 0.010; Ptch1, 70.9, p < 0.001)." (PMID 38308119, 2024). "Immunohistochemistry staining of GLI1, METTL3/14, and IGF2BP2 also confirmed that inhibitors against GLI1 or METTL3 decreased protein levels of GLI1, METTL3/14, and IGF2BP2 in tumor samples." (PMID 37149646, 2023). "Mechanistically, RCC2 induced cell growth, EMT, CSCs markers through Gli1; inhibiting Gli1 expression using siGli1 or GLI inhibitor suppressed cell progression in vitro and tumor growth in vivo." (PMID 38008751, 2023). "According to our results, TAMs‐released CCL22 stimulates the CCR4/FAK/AKT/Gli1 signaling in ESCC cells, providing a novel TAMs/intratumoral axis in tumor progression." (PMID 37846367, 2023). "In the adenohypophyseal tumor cell lines AtT-20 (corticotroph) and GH3 (lactotroph/somatotroph), expression of all four HH signaling components (SHH, PTCH1, PTCH2 and Gli1) is detected simultaneously." (PMID 37476499, 2023). "There are data showing that high upregulation of the HH pathway mediates the function of GLI1, facilitates the CXCL12-induced migration of cancer cells, and increases the metastatic potential of tumor cells." (PMID 37626893, 2023). "To find the minimal treatment time of GSK-J4, we treated the tumor cells with 30 μM of GSK-J4 in a time course and found that the Gli1 mRNA level decreased 50% after 6-7 hours." (PMID 36531063, 2022). "GLI1 can induce polycomb complex protein BMI-1, a stem cell regulator, which further increases NRP2 and α6β1 integrins activity, thereby accelerating tumor initiation." (PMID 35805056, 2022). "GLI1, SFRP4 and POLE genes were previously involved in tumorigenesis with a major contribution to tumor genomic instability." (PMID 36085309, 2022). "To further verify the tumour-promoting role of the Hh signalling pathway in EOC, we firstly examined the effects of GANT61 (the specific inhibitor of Gli1 and Gli2) by measuring the expression of Hh receptor, Ptch, and effectors, Gli1 and Gli2." (PMID 36358596, 2022). "GLI Family Zinc Finger 1 (GLI1)-mediated signaling and VEGF receptor neuropilin (NRP2) signaling form an autocrine loop to continuously promote tumor initiation in TNBC." (PMID 35805056, 2022). "The induction of GLI1 by EWSR1-FLI1 in multiple EwS cellular models and primary tumor specimens was also reported by several research groups." (PMID 35740349, 2022). "In particular, analysis of the hedgehog (HH) targets Gli1, MycN and Cyclin D2 proteins confirmed a similar SHH activity in the tumour samples of both backgrounds." (PMID 35839783, 2022). "In this study, we also examined stromal AR action in Gli1-lineage cells to promote PIN and tumor progression by injecting TM to 2-month-old Hi-Myc:ArL/Y:Gli1CreER/+ and Hi-Myc:Gli1CreER/+ mice and analyzed them at 6-months of age." (PMID 36323713, 2022).
tumor (continued). "In summary, our findings indicated that miR-378a-3p functions as a tumor suppressor in GC by directly targeting RAB31 and inhibiting GLI1/2 in the Hedgehog pathway." (PMID 36245214, 2022). "Taken together, these data uncover a regulatory mechanism by which AR deletion induces IGFBP3 expression in Gli1-lineage FB to block IGF1-signaling activation, further hindering prostatic basal epithelial cell-mediated oncogenesis and tumor development." (PMID 36323713, 2022). "Importantly, Gal-1 could enhance GLI1 expression in both fibroblast and tumor epithelium cells." (PMID 34572373, 2021). "A similar effect was also noted upon the inhibition of Hh-GLI1 in mice GBM xenografts, whereby concurrent treatment with cyclopamine and TMZ significantly inhibited their MGMT expression and tumor burden compared to TMZ alone." (PMID 34638233, 2021). "Significant overexpression of both GLI1 and GLI2 was found in intrahepatic CCC, when compared with non-tumor tissues (p < 0.001 and 0.05, respectively), suggesting a possible tumorigenic effect of SHH signaling during the development of CCC." (PMID 34948011, 2021). "In both tumour and normal vulval epithelium, expression of SHH ligand was localised to the cytosol; PTCH1 to the membrane, cytosol and nucleus; and GLI1, GLI2 and GLI3 to the cytosol and nucleus." (PMID 34480080, 2021). "Western blot analysis revealed that the levels of Gli1, BMI1, and SOX2 proteins in the tumor tissues from GANT61-treated mice were significantly lower than that from untreated controls." (PMID 33499351, 2021). "Further study by the same group revealed that GLI1 regulates the expression of EMT-inducing transcription factors, TWIST1 and SNAI1, to promote tumor-initiating cell-like properties and consequently chemoresistance in the resistant sublines." (PMID 34638233, 2021). "A xenograft assay validates the tumor growth-impeding effect and inhibition of CXCR4/SHH/GLI1 signaling cascade after ETV4 depletion." (PMID 34052833, 2021). "This study first uncovered that Gli1 transcriptionally activated MIRLET7BHG in HSCs, thus promoting HSC activation and HCC tumor growth." (PMID 33771969, 2021). "Targeting GLI1 using GLI1 siRNA nanoparticles significantly decreased GLI1 protein expression, inhibited gastric CSC tumor spheroid and colony formation, and suppressed cell migration and invasion." (PMID 34440799, 2021). "SMO inhibition results in transcription factors GLI1 and GLI2 remaining inactive, thus preventing expression of tumor-mediating genes within the hedgehog pathway." (PMID 34966484, 2021). "Increased mRNA levels of Gli1 and Ptch1 were seen in hsBCL9CT-24 or Bcl9-shRNA treated CT26 tumor cells, suggesting that BCL9 suppression activates CD155 expression via sonic hedgehog signaling." (PMID 34417435, 2021). "The heterogeneity of Gli1+ cells could also be important for therapies directed at manipulating Hh signaling in cancer, as this might have diverse effects that depend on the specific cell type targeted and its spatial location with respect to tumor cells, as we will discuss below." (PMID 33498528, 2021). "Although more in-depth studies are needed to clarify the mechanisms regarding the Gli1 regulation by LATS1 in CRC, our results strongly confirmed that the LATS1 is a tumor suppressor in CRC." (PMID 35003351, 2021). "For example, ZNF545, ZNF569, ZNF383, and ZNF331 are reported to act as tumor suppressor genes, while ZNF147, ZNF217, ZNF278, GLI1, and Evi9 promote tumor progression." (PMID 33566221, 2021). "In BC xenograft tumors, it significantly reduces tumor growth, which is accompanied by decreased PTCH, SMO, Gli1, and Gli2 expression." (PMID 34381705, 2021). "Knockdown of MVP or treatment with GANT61 significantly inhibited tumor growth, however, combined inhibition of MVP and GLI1 showed additive synergistic anti-tumor effect." (PMID 33637972, 2021).
tumor (continued). "Using publicly available databases, The Cancer Genome Atlas (TCGA), we compared expression levels of GLI1 and GLI2 in intrahepatic CCC with those in non-tumor liver tissues." (PMID 34948011, 2021). "We found that the expression of both Gli1 and HDAC2 was significantly upregulated in SHH‐MB tumors compared to WT cerebellum, indicating the over activation of SHH signaling in SHH‐MB tumor cells." (PMID 34480519, 2021). "Expression levels of SMO, GLI1, and PTCH1 as assessed in tumor tissue by real-time quantitative polymerase chain reaction (qPCR) did not predict a response to the addition of vismodegib." (PMID 33498528, 2021). "In GBM cells, the use of GANT-61, a specific inhibitor of Gli1 and Gli2, activates autophagy, inducing LC3-II expression, and by negatively modulating the expression of stemness markers and tumor proliferation." (PMID 34178638, 2021). "The Xena browser analysis indicated a higher gene expression of GLI1 and GLI2 in primary tumor tissue compared to normal tissue (GLI1; n = 786, p-value = 2.894 × 10−21, GLI1; n = 786, p-value = 6.001 × 10−33)." (PMID 32033067, 2020). "In these studies, both GLI1 and GLI2 regulate tumor growth, survival and epithelial-to-mesenchymal transition (EMT) upon stimulation by TGF-β1/2 in a SMO independent manner." (PMID 32245491, 2020). "The effects of DHA, cisplatin and the combination of cisplatin and DHA on Shh signaling was confirmed by testing the expression levels of nuclear Gli1, PTCH1, and Sox2 in tumor cells obtained from xenografts." (PMID 33363149, 2020). "Some authors have suggested that GANT61 acts selectively by inhibiting GLI1- and GLI2-mediated gene activation in different tumor cells." (PMID 32846867, 2020). "Next, we compared the expression levels of various HH target genes (GLI1, PTCH1, and PTCH2) in normal human primary esophageal epithelial cells and EAC cell lines derived from tumor samples." (PMID 32913560, 2020). "As we demonstrated that the intrinsic activation of SHH signaling was mainly due to Gli1 overexpression in response to EWS-FLI1, we then assessed the effects of the specific Gli inhibitor GANT61 on primary ES tumor growth." (PMID 33228057, 2020). "Overexpression of GLI1 and GLI2 leads to tumor development in transgenic mice, suggesting that GLI1 or GLI2 contribute to tumorigenesis." (PMID 32784501, 2020). "Expectably, LIN28B-AS1 was depleted in LIN28B-AS1 KO tumor tissues, where IGB2BP1-dependent mRNAs, including Gli1, Myc, and IGF2, were decreased." (PMID 32917856, 2020). "Positive correlation (arbitrary threshold: r > 0.25) between the GLI1 and GLI2 genes was observed in 33/37 tumor types, representing 92.5% (21,825/23,587) of patients." (PMID 32879407, 2020). "IBET-151 also attenuates tumor growth of EAC-PDXs and does so in an on-target manner as it reduces the expression of GLI1." (PMID 32913560, 2020). "We had limited samples with adequate RNA to measure Gli-1 and PATCH expression using RT-PCR (n = 8) largely because of limited tumour tissue." (PMID 31857726, 2020). "Among Gli1 regulated ABC transporters, ABCG1 was expressed at significantly higher levels in cancer tissues respect to non-tumour tissues and in CD133+ cancer cells respect to CAFs." (PMID 32814794, 2020). "We examined the expression correlations of GLI1/2 with TGFB and HH genes in 152 distinct transcriptome datasets totaling over 23,500 patients and representing 37 types of neoplasms." (PMID 32879407, 2020). "MDB5 downregulated ALDH1, CD44, Oct-3/4 (key tumor markers of pancreatic CSC), Bcl-2, GLI-1 and SHH and upregulated Bax." (PMID 32962123, 2020). "Protein levels of Gli1, Myc, and IGF2 were significantly downregulated as well in LIN28B-AS1 KO tumor tissues, with IGF2BP1 protein levels unchanged." (PMID 32917856, 2020). "Pin1 overexpression increased the Gli1 protein level, a regulator of the EMT, by increasing the protein stability of Gli1, and promotes EMT and tumor cell motility." (PMID 33162791, 2020).
tumor (continued). "GLI1 activation drove LSCC growth and treatment with combinatorial PI3K and GLI1 antagonists induced tumor regression in vivo." (PMID 32108165, 2020). "In co-cultures, down-regulation of GLI1, SMO, and PTCH1 in the stroma correlated with reduced tumor growth rates in xenografted tumors and cell cultures, confirming a paracrine interaction." (PMID 31658643, 2019). "Immunostaining revealed that there was significantly decreased expression of GSC-related factors, including GLI1, SOX2, and vimentin in the background of PFD treatment, but residual tumor in TMZ treatment group still exhibited the expression of those proteins." (PMID 31492002, 2019). "This paracrine mechanism is characterized by binding of tumor-secreted Hh ligands (SHH, Indian Hedgehog (IHH), or Desert Hedgehog (DHH)) to PTCH1 receptors, and elevated levels of GLI1, GLI2, PTCH1, and SMO genes in the tumor-adjacent stroma." (PMID 31658643, 2019). "This sensitivity to GLI1 antagonist is in agreement with previous reports indicating that targeting of GLI1/2 function through GANT58 and GANT61 decreased tumor growth of prostate and breast cells." (PMID 31658643, 2019). "In one study, hyperactivation of the pathway by overexpression of GLI1 under the MMTV promoter in the mammary epithelium was sufficient to induce hyperplastic lesions and tumor development in mice." (PMID 31027259, 2019). "GLI-dependent Hh activation induced by the overexpression of GLI1 target genes, such as GLI1 and PTCH1, is observed in MM tumor cells." (PMID 30987263, 2019). "To explore the role of the GLI family proteins (include Gli1, Gli2, Gli3) in the onset and development of HCC, we examine tumor and matched adjacent normal tissue samples from 10 patients with HCC." (PMID 31616295, 2019). "Toftgard and co-workers developed a GLI1 inhibitor, GANT61, that is effective at inhibiting tumour cell growth in vitro and in vivo." (PMID 30068568, 2018). "We examined the expression levels of proliferative marker Ki67, metastasis marker Gli1, and VEGFR2 in tumor tissues derived from the xenografts." (PMID 29976975, 2018). "Univariate analysis revealed that Gli1 expression, venous invasion, TNM staging, depth of tumor invasion, lymph node metastasis, size of tumor, differentiation, neural invasion were associated with an inferior survival duration (P < 0.05)." (PMID 29321573, 2018). "Since GLI1 is known as an oncogene, our results also provide further evidence to support MEKK2/3 suppress Hh-dependent tumor cell growth by regulating GLI1 activity." (PMID 29662197, 2018). "In the present study, we showed that a SMO inhibitor, AY9944 and a GLI-1 inhibitor, GANT61 improved the sensitivity for anti-cancer drugs in tumor ALI organoids." (PMID 29642386, 2018). "Similarly, the SHH transcript is localized to tumor tissue whereas GLI1 and PTCH1 are detected in both the tumor and the stroma, proving the hypothesis that SHH and its target genes function in a paracrine manner to regulate the development of subsets of esophageal cancers." (PMID 30423843, 2018). "They then demonstrated that GlaB inhibits GLI1-dependent BCC cell growth in vitro and BCC tumor growth in ASZ001 BCC allografts in vivo." (PMID 29615568, 2017). "Immunohistochemical analyses of GLI1, GLI2 and PTCH1 demonstrated that GANT61 was able to specifically inhibit Hh signaling in the tumor." (PMID 28208838, 2017).